PXMP4 (peroxisomal membrane protein 4)
Synonyms: PMP24
Tractability: Antibody: UniProt predicts a signal peptide or a membrane-spanning region. PROTAC: ubiquitination databases record sites on it; its protein half-life has been measured.
Gene: Protein-coding gene on chromosome 20 (33,702,758 to 33,720,319, reverse strand). Ensembl gene ENSG00000101417.
Subcellular location: Peroxisome membrane
Subcellular location (Human Protein Atlas): Peroxisomes; Nucleoli fibrillar center
Pathways (Reactome):
Protein localization: Class I peroxisomal membrane protein import
Gene Ontology:
Molecular function: protein binding
Cellular component: peroxisomal membrane; peroxisome; cytosol
Genetic constraint (gnomAD): Loss-of-function variants: 16 observed, 21.99 expected, observed/expected ratio (o/e) 0.73, 90% interval 0.49 to 1.11. The upper end of that interval is the gene's LOEUF score, 1.11, which puts it in group 4 of 6, group 1 being the genes least tolerant of losing a copy. Missense variants: 232 observed, 282.85 expected, observed/expected ratio (o/e) 0.82, 90% interval 0.74 to 0.91. Synonymous variants: 124 observed, 127.97 expected, observed/expected ratio (o/e) 0.97, 90% interval 0.84 to 1.12.
Homologues: Orthologues: chimpanzee PXMP4 (99% identical), macaque PXMP4 (97% identical), rabbit PXMP4 (85% identical), rat Pxmp4 (83% identical), guinea pig PXMP4 (81% identical), mouse Pxmp4 (81% identical), tropical clawed frog pxmp4 (74% identical), zebrafish pxmp4 (72% identical), Caenorhabditis elegans pxmp-4 (50% identical).
Diseases named in the same sentence as PXMP4 in open-access papers:
PXMP4 is named in the same sentence as 10 diseases in open-access papers, as found by Europe PMC text mining. Sharing a sentence is not in itself a finding about the gene and the disease. The quoted sentences say what the papers report.
prostate carcinoma (5 papers, 2018 to 2022). A carcinoma that arises from epithelial cells of the prostate gland. "In addition to the enzymes of the peroxisomal branched-chain fatty metabolism, the peroxisomal membrane protein PMP24/PXMP4 has been associated with the development of prostate cancer." (PMID 30219925, 2018). "Silencing of PXMP4 expression was found during the tumorigenesis of prostate cancer cells and upregulation of PXMP4 expression in arteries is associated with obesity." (PMID 33505966, 2020).
gastric cancer (1 paper, 2025). A primary or metastatic malignant neoplasm involving the stomach. "Similarly, PXMP4—a PMP recently implicated in gastric cancer cell proliferation, invasion, and migration via the phosphatidylinositol 3-kinase (PI3K)/Akt signaling pathway —also exhibits significantly reduced mRNA expression in PCa tissues." (PMID 40647540, 2025).
viral infections (1 paper, 2024). "Among the top 10 downregulated genes, SREBF1, FGFR4, CRAT and PXMP4 showed a similar decrease following different viral infections." (PMID 39625479, 2024).
tumor (5 papers, 2014 to 2022). "Although various somatic mutations and hypermethylation resulting in the silencing of PXMP4 in humans have been reported for several types of cancer, its role in tumor development, as well as its physiological function, has remained unknown." (PMID 35169201, 2022). "Through Oncomine, Human Protein Atlas (HPA) and the Clinical Proteomic Tumor Analysis Consortium (CPTAC), three K-DEPGs (HSD17B4, ACAA1, and PXMP4) were confirmed to be down-regulated in NSCLC at both mRNA and protein level." (PMID 32265992, 2020). "HSD17B4, ACAA1, and PXMP4 were all strong expressed in lung (pneumocytes) while there was a negative to moderate expression of HSD17B4 and ACAA1 in the cytoplasm or membrane of LUSC and LUAD tumor cells." (PMID 32265992, 2020). "However, considering the differences in their prognostic effects, regulations, correlations with tumor purity and immune infiltrations effects between the two subtypes, further study is needed to investigate the specific functions of HSD17B4, ACAA1, and PXMP4 in LUSC and LUAD, respectively." (PMID 32265992, 2020).
cancer (2 papers, 2020 to 2022). A tumor composed of atypical neoplastic, often pleomorphic cells that invade other tissues. "Expressional differences of HSD17B4, ACAA1, and PXMP4 between NSCLC cell lines with different anti-cancer drug sensitivity." (PMID 32265992, 2020).
metabolic disorders (1 paper, 2022). "Notably, the ileal lncRNA NONMMUT040618 and its target mRNAs (Pxmp4, Pnpla3, and Car5a), which were involved in lipid and amino acid metabolism-related pathways, might play vital roles in the remission of metabolic disorders after DJB." (PMID 35464075, 2022).
PXMP4 also shares sentences with these, for which no sentence is quoted: lung carcinoma (1 paper); non-small cell lung carcinoma (1); Obesity (1); ovarian carcinoma (1).